CDK12 (cyclin dependent kinase 12)
Diseases named in the same sentence as CDK12 in open-access papers (continued):
Sharing a sentence is not in itself a finding about the gene and the disease.
prostate carcinoma (continued). "In prostate cancer, inactivation or loss of CDK12 leads to a unique genomic instability pattern characterized by widespread focal tandem duplications throughout the genome, some of which may occur in coding regions, resulting in gene fusions and potential fusion-induced neoantigens." (PMID 39895499, 2025). "Meanwhile, CDK12 deficiency‐caused energy metabolism reprogramming may suggest targeting mitochondrial ETC as a promising efficient treatment strategy for CDK12 mutated prostate cancer patients." (PMID 38736108, 2024). "In advanced prostate cancer, a study identified CDK12 mutant cases associated with elevated neoantigen burden and increased tumor T cell infiltration and summarized that CDK12 inactivation defines a distinct class of metastatic castration-resistant prostate cancer that may benefit from ICI therapy." (PMID 39706915, 2024). "However, it remains unclear which treatment is truly effective for CDK12-altered prostate cancer or whether CDK12 monoallelic loss can be treated in the same manner as biallelic loss." (PMID 36271301, 2022). "Therefore, CDK12-mutated cancers might constitute a separate subgroup of prostate cancer in which immunotherapy may be effective." (PMID 35328633, 2022). "We reasoned that our CDK12NULL patients could represent the previously reported fraction of breast cancer patients harboring CDK12 loss-of-function mutations, a condition also described in other cancers, including ovarian and prostate cancer, and associated with aggressive disease course." (PMID 35550508, 2022). "For instance, CDK12 alterations are notably frequent in breast, colorectal, pancreatic and prostate carcinomas." (PMID 41491919, 2026). "This has prompted a shift toward mechanistic markers that reflect the inherently low immunogenicity of prostate cancer, such as mismatch repair deficiency (dMMR), a microsatellite instability-high (MSI-H) phenotype, and CDK12 gene alterations." (PMID 40227610, 2025). "To understand the underlying mechanisms, we performed spatial transcriptomic analyses on metastatic castration-resistant prostate cancer (mCRPC) samples with either inactivated or wild-type CDK12." (PMID 40955658, 2025). "Inactivation of cyclin-dependent kinase 12 (CDK12) defines an immunogenic molecular subtype of prostate cancer characterized by genomic instability and increased intratumoral T cell infiltration." (PMID 40955658, 2025). "Another study found that high CDK12 levels was associated with increased expression of immune checkpoint factors PDCD1 and CTLA-4 in prostate cancer, supporting the concept of combining CDK12 inhibitors with immune therapy." (PMID 40163908, 2025). "Our previous work identified CDK12 as a critical regulator of prostate cancer (PCa) cell survival under sustained enzalutamide exposure, though the precise mechanism remains to be elucidated." (PMID 40605142, 2025). "For example, a recent study identified CDK12 to be critical for prostate cancer cell survival and its inhibition suppressed AR signalling." (PMID 40163908, 2025). "Human ovarian and prostate cancers with CDK12 inactivation frequently display a DNA damage pattern characterized by tandem duplications." (PMID 40504161, 2025). "The mechanisms linking CDK12 inactivation to increased intratumoral T cell presence in advanced prostate cancer and the development of preneoplastic lesions with lymphocytic infiltration in the murine prostate epithelium have remained unclear." (PMID 40955658, 2025).
prostate carcinoma (continued). "BAP1 alterations stood out in kidney (9.9%) and cervix (2.9%) cancers, with ATM most frequent in bladder cancer (7.7%), CDK12 notable in prostate cancer (7.4%), and FANCA prominent in melanoma (3.1%)." (PMID 40420266, 2025). "CDK12 inhibits insulin-like growth factor binding protein 3 (IGFBP 3) in regulating angiogenesis in advanced prostate cancer." (PMID 39790460, 2025). "CDK12BAL cells showed a vulnerability to targeting of CDK13 by sgRNA or CDK12/13 inhibitors and in vivo treatment of prostate cancer xenograft lines showed that tumors with CDK12BAL responded to the CDK12/13 inhibitor SR4835, while CDK12-intact lines did not." (PMID 39071291, 2025). "Pharmacological inhibition of CDK12/13 profoundly attenuates in vitro proliferation of prostate cancer cells and reduces tumor burden in subcutaneous mouse xenograft models." (PMID 39353441, 2024). "As expected, the overall phosphorylation level of RNA Pol II in prostate cancer cells was significantly decreased with CDK12 knockout." (PMID 38736108, 2024). "PARP inhibitors (PARPi) targeting HR repair defects have been used in clinical trials of patients with CDK12‐inactivated prostate cancer." (PMID 38736108, 2024). "Further studies are needed to approach the causes of MHC disruption derived from “Soft” alterations that occur in CDK12-mut prostate cancer." (PMID 38704603, 2024). "By contrast, primary prostate cancer (PCa) sequences in The Cancer Genome Atlas (TCGA) revealed biallelic CDK12 alterations in only 6/498 cases (1.2%)—a finding indicating enrichment of CDK12 inactivation in metastatic disease." (PMID 39368479, 2024). "Soon afterwards, the FDA granted further approval for the application of talazoparib in the treatment of prostate cancer patients exhibiting mutations in HRR pathway genes, encompassing CDK12 and RAD51C (Akbıyık and Ürün, 2023)." (PMID 38953104, 2024). "Our findings show that energy and lipid metabolism in CDK12‐deficient CRPC work together to drive CRPC progression and provide a metabolic insight into the worse prognosis of CDK12‐deficient prostate cancer patients." (PMID 38736108, 2024). "The critical dependency of prostate cancer cells on CDK12 and CDK13 for proliferation was further recently corroborated by CRISPR-mediated gene editing." (PMID 39353441, 2024). "Patients with prostate cancer with certain RAD51B or CDK12 SNVs, including RAD51B R47*, are FDA-approved for treatment with olaparib (a PARP inhibitor)." (PMID 38975340, 2024). "We found that CDK12-d prostate cancers had an increased number of mid- and large-sized tandem duplications 100 kb to 10 Mb, compared to CDK12-WT." (PMID 36883553, 2023). "A retrospective study of 60 men with CDK12-altered advanced prostate cancer showed that of the 9 men who received PD-1 inhibitor therapy, 33% had a PSA response and the median PFS was 5.4 months." (PMID 37842236, 2023). "Repression of CDK12 with covalent inhibitor THZ531 exerts an anti-prostate cancer effect; therefore, CDK12 represents a druggable target of prostate cancer." (PMID 36969009, 2023). "A small cohort of CDK12-mutant prostate cancer cases suggested a minor but positive effect of PD-1 blockade therapy." (PMID 38067312, 2023). "This notion is particularly important given that the function of CDK12 can be inhibited by small-molecule inhibitors that have already been explored related to, e.g., breast, ovarian, and prostate cancer therapy." (PMID 38132164, 2023). "In conclusion, we present 12 Japanese cases of CDK12-altered prostate cancer from various backgrounds, some of which had an aggressive course, while others achieved long-term survival with existing medical treatment." (PMID 36271301, 2022).
prostate carcinoma (continued). "We present the first case series of 12 Japanese patients with CDK12-altered prostate cancer from various backgrounds." (PMID 36271301, 2022). "CDK12-altered prostate cancer is a heterogeneous disease, and accumulating cases with detailed information leads to precision oncology." (PMID 36271301, 2022). "Numerous genes located in 17q12 region have been implicated in diverse cancers, such as ERBB2 for gastric cancer 38 and breast cancer 39, CDK12 for prostate cancer 40, and STARD3 for breast cancer." (PMID 36147475, 2022). "Prostate cancer harboring cyclin-dependent kinase 12 (CDK12) abnormalities is a hot topic due to its distinctive clinical features, such as sensitivity to immune checkpoint inhibitors." (PMID 36271301, 2022). "Mutations in CDK12 have been shown to confer sensitivity to PARP inhibitors in breast and ovarian cell lines and clinical trials in prostate cancer." (PMID 35643464, 2022). "We have treated 12 cases of CDK12-altered prostate cancer from various backgrounds, including monoallelic and biallelic loss and localized and metastatic cancer." (PMID 36271301, 2022). "As several studies have demonstrated that copy number of specific regions frequently increased in prostate cancer with CDK12 alteration, we examined the copy numbers of representative gene loci with CDK12 alterations." (PMID 36271301, 2022). "In prostate cancer, CDK12 inactivation has shown more aggressive clinical features including greater proportion of distant metastases and shorter time to PSA progression." (PMID 34898046, 2022). "Of the patients with prostate cancer who underwent genomic testing at Keio University Hospital (Tokyo, Japan) between 2015 and 2021, 12 had possibly deleterious CDK12 gene alterations." (PMID 36271301, 2022). "Since then, there has been a growing number of studies on CDK12-altered prostate cancer, with most reporting that patients with this type of cancer have poor prognosis." (PMID 36271301, 2022). "Accumulating cases with detailed information will contribute to precision oncology for CDK12-altered prostate cancer." (PMID 36271301, 2022). "Whole-exome and transcriptome profiling of 150 metastatic castration-resistant prostate cancer found that more than 19% of them have at least one mutation in BRCA1, BRCA2, ATM and CDK12." (PMID 36371386, 2022). "Although prostate cancer is a “cold tumor” in the traditional sense of immunotherapy, patients with cyclin-dependent kinase 12 (CDK12) and mismatch repair (MMR) gene alterations often benefit from immune checkpoint inhibitor (ICI) therapy." (PMID 36362304, 2022). "This case series suggests that a heterogeneity exists in patients with prostate cancer with CDK12 alterations." (PMID 36271301, 2022). "In our cohort, there was a lack of response to PARP inhibition, which is in concordance with previously published data that also show poor responses to PARP inhibitors in CDK12‐altered prostate cancer." (PMID 34898046, 2022). "The inactivation of CDK12 in prostate cancer is related to the resistance to endocrine therapy, paclitaxel, and PARP inhibitors and sensitivity to immunotherapy." (PMID 38089758, 2022). "CDK12-mutant prostate cancer patients have a higher likelihood of response to immunotherapy than an unselected metastatic prostate cancer population from the pilot clinical study." (PMID 32570740, 2020).
prostate carcinoma (continued). "Preliminary data from four prostate cancer patients with CDK12-altered prostate cancers showed in two of these patients, response to treatment with the immune checkpoint blockade therapy." (PMID 31366128, 2019). "CDK12-mutant prostate cancers are baseline diploid and have an excess of focal tandem duplications; furthermore, these tumors have a peculiar transcriptional profile." (PMID 31366128, 2019). "Biallelic CDK12 inactivation was highest in prostate cancer (1.8%), followed by ovarian (1.0%) and bladder cancers (0.5%)." (PMID 31360735, 2019). "Kenpaullone has been reported to have therapeutic potential for several cancer types such as breast and prostate cancers via inhibition of GSK3β and CDK12,22–26." (PMID 31296906, 2019). "In prostate cancer organoids, CDK12 inactivation enhances androgen-receptor (AR) signaling and induces enzalutamide resistance, whereas combined inhibition of CDK12/13 (THZ-531) and AR blockade (bicalutamide, apalutamide, or enzalutamide) exerts synergistic cytotoxicity." (PMID 41491919, 2026). "On the other hand, the presence of similar collections of CD4(+) and CD8(+) T cells in our Cdk12-null mouse prostate cancer model suggests other factors (such as increased proinflammatory signaling) might also be in play." (PMID 40504161, 2025). "In prostate cancer, CDK12 plays a dual role as both a tumor suppressor and an oncogene." (PMID 39800748, 2025). "In prostate cancer, CDK12-mutant tumours exhibit higher T cell infiltration and expansion of T cell clones along with increased expression of chemokines and their receptors; accordingly, tumours with CDK12 loss-of-function mutations showed a positive response to PD-1 inhibitors." (PMID 40163908, 2025). "To test this hypothesis with existing clinical data, we identified prostate cancer patient samples with inactivation of the CDK12-gene from the TCGA, Firehose Legacy and SU2Cancer datasets." (PMID 40186208, 2025). "The extent to which CDK12 loss confers sensitivity to single-agent PARP inhibition remains contentious; in prostate cancer, the tandem duplication resulting from biallelic CDK12 loss results in increased neoantigen generation and enhanced sensitivity to immunotherapy." (PMID 40593568, 2025). "Our prior work in numerous prostate cancer models revealed the two kinases to have a synthetic lethal relationship—such that genetic ablation or pharmacologic inhibition of CDK13 preferentially impairs tumor cell survival in the setting of CDK12 inactivation." (PMID 40504161, 2025). "We previously showed CDK12 to be a bona fide tumor suppressor gene in prostate cancer." (PMID 40504161, 2025). "Moreover, pathways associated with CDK12 loss showed considerable concordance between HGSC samples and prostate cancer with presumptive CDK12 inactivation." (PMID 40504161, 2025). "The expression of CDK12 was lower in prostate cancer samples compared to normal prostate tissue, and CDK12 levels were further significantly lower in metastatic patients than in early‐stage patients, suggestive of its tumour suppressive role in prostate cancer progression." (PMID 38736108, 2024). "The CDK12 results are striking given an alteration prevalence of 5% to 7% according to the literature and that limited clinical data indicate poor prognosis with minimal benefit from PARP inhibitor monotherapy in patients who have prostate cancer and CDK12 alterations." (PMID 38049622, 2024). "employ mouse models to define Cdk12 as a bona fide prostate cancer tumor suppressor gene." (PMID 39368479, 2024). "CDK12 regulates genes related to HR and impacts genomic stability in prostate cancer." (PMID 38736108, 2024). "In addition, prostate cancer had a high rate of therapeutic target mutations, including BRCA1/2, CDK12 mutations, and ERBB2 amplification." (PMID 36251535, 2023).
prostate carcinoma (continued). "Prostate cancers with dMMR genes, MSI-H, and CDK12 biallelic alterations are reported to be associated with higher TMB and neoantigen loads, which may enhance antitumor immunity." (PMID 37686423, 2023). "CDK12 is also overexpressed in some human epidermal growth factor receptor 2–positive breast cancers and a subset of endoplasmic reticulum–positive breast and prostate cancers." (PMID 37205756, 2023). "Despite this, dMMR and CDK12-altered prostate cancers have more aggressive biology." (PMID 37842236, 2023). "A similar mechanism has been previously suggested for prostate cancer, since patients with pathogenic germline CHEK2 mutations displayed a significantly higher prevalence of the somatic CDK12 mutation than unselected prostate cancer patients from the TCGA cohort." (PMID 35267514, 2022). "Moreover, to establish a therapeutic strategy for CDK12-altered prostate cancer, clinical trials based on CDK12 allelic status and FTD burden are expected." (PMID 36271301, 2022). "Because CDK12 mutation is one of the characteristic features of prostate cancer and is not seen in clonal hematopoiesis, we considered that false positives are unlikely." (PMID 36271301, 2022). "Using the WGS data, we assessed the presence of variants and/or mutations in several genes that are known to be frequently mutated in prostate cancer (BRCA1, BRCA2, RB, PTEN, CDK12, PI3K, ADP-ribose, PIK3GA, PIK3CB and PIK3R1, AKT, CYP17, IGF 1, EGF, and BCL2)." (PMID 36643868, 2022). "This is the first Japanese prostate cancer case series with CDK12 alterations." (PMID 36271301, 2022). "Interestingly, very recent analyses have revealed the presence of focal tandem duplications in many other cancers with a low incidence (<2%) of CDK12 inactivation, suggesting their occurrence in addition to ovarian and prostate cancers." (PMID 34316683, 2020). "Genomic alterations in CDK12 were documented in ∼30 tumour types with an incidence of up to 15% of sequenced cases with molecular consequences best studied in ovarian, breast and prostate cancers." (PMID 34316683, 2020). "In addition, CDK12-mutant prostate cancers are characterized by increased gene fusions, fusion-induced neoantigen open reading frames and high immune infiltration." (PMID 32570740, 2020). "Notably, CDK12 mutant prostate cancer tumours exhibit synthetic dependence on recurrent gains in several genes involved in the regulation of the cell cycle and DNA replication such as MCM7,CCND1 or RAD9A." (PMID 34316683, 2020). "CDK12 may be inactivated in patients with metastatic castration-resistant prostate cancer, and may make tumors more responsive to PD-1 inhibitors (CDK12 Changes Telling in Prostate Cancer, 2018)." (PMID 32063918, 2019). "Inactivating CDK12 alterations have been reported in ovarian and prostate cancers and may have therapeutic implications; however, the prevalence of these mutations across other cancer types is unknown." (PMID 31360735, 2019). "BRCA2 and ATM mutated, as well as ETS-fusion-positive prostate cancers have the highest percentage of gains, while the majority of CDK12-mutant tumors do not have any change in ploidy." (PMID 31366128, 2019). "A recent study provided evidence that prostate cancers bearing biallelic CDK12 deletion may represent a peculiar tumor subtype." (PMID 31366128, 2019). "Given the critical role of NF-κB in mediating androgen-independent phenotypes in prostate cancer, it is tempting to speculate that CDK12 may also play a role in prostate cancer progression and therapy resistance by stimulating this factor, although this concept requires further investigation." (PMID 40163908, 2025). "However, the functions of CDK12 in prostate cancer are complex and pleiotropic." (PMID 40163908, 2025).